SIGLEC15 (sialic acid binding Ig like lectin 15)
Diseases named in the same sentence as SIGLEC15 in open-access papers (continued):
Sharing a sentence is not in itself a finding about the gene and the disease.
tumor (continued). "The expression of HAVCR2, PDCD1LG2 and SIGLEC15 is prominently different in normal and tumor samples." (PMID 37065485, 2023). "Next, we generated Siglec15 gene knockout Ana-1 cell lines (Ana-1-KO) to investigate the role of Siglec-15 on the function of tumor infiltrating macrophages." (PMID 37234161, 2023). "In this study, we analyzed Siglec15 expression within stromal area (SA) and tumor area (TA), and its relationship with tumor-infiltrating lymphocytes (TILs) in COAD and mismatch repair-proficient (MMR-p) COAD." (PMID 37859817, 2023). "Tumor Siglec15 can be downregulated by IFN-γ, which is the dominant cytokine required for PD-L1 induction." (PMID 37859817, 2023). "Siglec15(SA) expression were poor prognosis for patients—under 68 years old, male, left side tumor, high stage, infiltrative tumor, and low CD8+ T cell density." (PMID 37859817, 2023). "As Siglec15 is broadly upregulated in human cancer cells and tumor infiltrating myeloid cells, we detected the Siglec15 expression in TA, SA and whole cells." (PMID 37859817, 2023). "Tumor‐associated macrophages protect cancer cells through eliminating the anti‐tumor T cells by overexpressing PD‐L1, PD‐L2, CD80, and Siglec‐15." (PMID 34898004, 2022). "The expression of CD274, CTLA4, LAG3, PDCD1, PDCD1LG2 and SIGLEC15 was significantly different between adjacent normal tissues and tumor tissues." (PMID 36588699, 2022). "Expressions of CD274, CTLA4, LAG3, PDCD1, PDCD1LG2, and SIGLEC15 were shown to be significantly different between normal and tumor samples in immune checkpoint analysis." (PMID 36588699, 2022). "In conclusion, we found that SIGLEC15 mRNA expression was upregulated in tumor tissue and validated that by TMA." (PMID 36159823, 2022). "SIGLEC15 not only plays a biological role in osteoclast differentiation but also in microbial infection and tumor microenvironment." (PMID 33796453, 2021). "Additional to this and perhaps even more notable, the responders also downregulate Siglec15, a critical immune suppressor that is commonly upregulated on human cancer cells and tumor-infiltrating myeloid cells." (PMID 34253827, 2021). "Among the upregulated genes, PLA2G2D and SIGLEC15 had a putative function in immunosuppression or promoting tumor growth and metastasis." (PMID 34722496, 2021). "Studies have shown that SIGLEC15 expressed on the surface of tumor cells can bind to the corresponding receptors on the surface of CD8+ T cells, thereby inhibiting its function." (PMID 35155218, 2021). "Siglec‐15 promotes the secretion of transforming growth factor‐β in tumor‐associated macrophages through the DAP12–Syk pathway, which promotes tumor progression through regulating the tumor microenvironment." (PMID 33015999, 2020). "Moreover, the significantly suppressed tumor sizes in the SHES of mice suggest that the overall role of SIGLEC15 in primary BRCA tumors is inhibitory, which is consistent with previous research." (PMID 41158758, 2026). "Consequently, SIGLEC15 correlates with tumor immune infiltration, molecular subtypes, and BRCA progression and prognosis." (PMID 39541298, 2024). "Additionally, three genes (PRDM1, IFI27 and SIGLEC15) were highly expressed in tumor tissues but were also favorable prognostic factors, suggesting a paradox: they promote carcinogenesis but inhibit tumor progression." (PMID 38287330, 2024). "Additionally, using TNMplot to study the expression differences between healthy and tumor samples after excluding adjacent non-tumor tissues also revealed high expression of SIGLEC15 mRNA." (PMID 39541298, 2024). "For another, Siglec‐15 shows dramatic immunosuppression on T cell response and Siglec‐15 inhibition reverses T cell inhibition, suggesting Siglec‐15‐specific antibody may restore tumor immunity and inhibit tumor growth." (PMID 38725348, 2024).
tumor (continued). "In our study, we found that high PSMB2 expression may induce the upregulation of CD274, CTLA4, HAVCR2, LAG3, PDCD1, PDCD1LG2 and SIGLEC15, which are molecules on immune cells that facilitate tumor immune escape." (PMID 38467767, 2024). "As a immunosuppressive molecule, Siglec‐15 in different expression site or various tumor type could give rise to multifarious activities in TME." (PMID 38725348, 2024). "Furthermore, the high levels of PD-1, PD-L1, CTLA-4, LAG-3, SIGLEC15, and TIGIT were associated with poor prognosis and immunosuppression of the tumor microenvironment in ccRCC." (PMID 37175461, 2023). "Interestingly, this study has given insights into the possible interactions between miRNAs and oncogenes for considerable strategies for the treatment of SIGLEC15 positive CRC tumours." (PMID 37869015, 2023). "Siglec15 is broadly expression on human cancer cells and tumor infiltrating myeloid cells, and it has been reported that SIGLEC15+ tumor-associated macrophage, rather than SIGLEC15+ PDAC cells, correlated with poor prognosis in PDAC31." (PMID 37859817, 2023). "If the treatment with Siglec15 antibody could recruit more CD8+ T cells to the tumor, it may convert the MMR-p COAD from a “cold” to a “hot” tumor." (PMID 37859817, 2023). "Combined with the previous findings, we speculated that the elevated SEMA5B may interfere with SIGLEC15 expression through some unknown mechanism, thus affecting the immune effect of cytotoxic T cells and ultimately prolonging the survival of tumor patients." (PMID 35480320, 2022). "In addition to the PD-1/PD-L1 pathway, SIGLEC15 is another important tumor-immune escape mechanism and represents a new kind of immune checkpoint inhibitor." (PMID 35198632, 2022). "A recent study found that SIGLEC15 glycosylation promoted tumor growth and immune escape." (PMID 36479122, 2022). "In this study, we found that SEMA5B levels showed a negative correlation with SIGLEC15 in KIRC, suggesting that SEMA5B may effect of SIGLEC15 on tumor immunity." (PMID 35480320, 2022). "We next assessed the role of SIGLEC15 in anti-tumor activities of T cells." (PMID 34722496, 2021). "Furthermore, the inhibition or knockout of SIGLEC15 expression can improve the anti-tumor ability of T cells in mice." (PMID 34917126, 2021). "For example, the number and types of tumor-infiltrating immune cells, tumor cells, immunomodulators, and the extracellular matrix composition may have an effect on the level of macrophages and the expression of Siglec15." (PMID 33537076, 2021). "Strikingly, siRNA-mediated silencing of SIGLEC15 in SN increased the secretion of anti-tumor cytokines, including IL2, IFN-γ, and TNF-α, suggesting that inhibiting SIGLEC15 expression in SNs could restore T cell function." (PMID 34722496, 2021). "When further looking at the population of mice with the most distinct RNA profile (as thought to be responders to treatment) we find that amongst the downregulated MDSC genes is Siglec15, a known immune suppressor broadly expressed on human cancer cells and tumor infiltrating myeloid cells." (PMID 34253827, 2021). "Finally, further experiments are needed to determine the expression profiles of Siglec15 in tumor cells and TIICs." (PMID 33537076, 2021). "In addition, this study suggested that SIGLEC15 would be a new immune therapeutic target for harnessing T cells in tumor lymph nodes." (PMID 34722496, 2021). "Also, in diffuse glioma, deep deletion of SIGLEC family genes was common in comparison to 32 other types of tumor, and SIGLEC15 seemed to be deeply deleted in various tumors, while SIGLEC16 was amplified in mutating cancer types." (PMID 33240817, 2020). "By profiling the immune modulators, we found that some suppressors, including B7‐H3, LAG3, VEGFB and Siglec‐15, are significantly upregulated in tumor tissues, which may contribute to the relatively suppressive immune microenvironment in SCCE." (PMID 33033616, 2020).
tumor (continued). "Similarly, Siglec15 is upregulated in tumours such as COAD, BLCA, KIRP, THCA and KICH." (PMID 38268823, 2024). "Since former studies have found SIGLEC1 (CD169), SIGLEC2 (CD22), SIGLEC3 (CD33), SIGLEC7, SIGLEC9, and SIGLEC15 expressed by immune cell populations could be manipulated by tumor cells to escape immune surveillance, we focused on the five SIGLEC family members." (PMID 33240817, 2020). "Numerous transcripts related to immunological checkpoints, including SIGLEC15, PDCD1LG2 (PD-L2), TIGIT, PDCD1 (PD-1), CD274 (PD-L1), CTLA4, LAG3, and HAVCR2 (TIM3), are integral to tumor immune evasion mechanisms." (PMID 41194934, 2025). "In tumor microenvironment (TME), tumor cells with high Siglec‐15 expression often demonstrate highly malignant features and behaviors." (PMID 38725348, 2024). "The results demonstrated a positive correlation between FANCD2 and immune checkpoints in most tumor tissues, including CTLA4, HAVCR2, LAG3, PDCD1, PDCD1LG2, SIGLEC15, TIGIT, and particularly CD274." (PMID 38443946, 2024). "As the Siglec15 and PD-L1 expression levels influence the tumor microenvironment 15, 30, we were curious regarding CD4+ and CD8+ tumor infiltrating lymphocytes (TILs) in COAD." (PMID 37859817, 2023). "In this review, we present the proliferative role of 15 immune checkpoints, including PD1, PD-L1, FGL1, CD155, CD47, SIRPα, CD276, IDO1, SIGLEC-15, TIM3, Galectin-9, CD70, CD27, 4-1BBL, and HVEM, in tumor progression." (PMID 36358792, 2022). "SIGLEC15, PDCD1LG2(PD-L2), TIGIT, PDCD1(PD-1), CD274(PD-L1), CTLA4, LAG3, and HAVCR2(TIM3) are immunological checkpoints that perform a vital function in tumor immune evasion." (PMID 35840882, 2022). "CTLA4, HAVCR2, PVRL2, PDCD1, SIGLEC15, TIGIT, and VTCN1 expression levels were higher in tumor tissues, while CD244, LAG3, PDCD1LG2, and CD274 expression levels were found to be lower." (PMID 35923695, 2022). "The 20 most highly and lowly expressed genes were presented, and we noted that the SIGLEC family genes SIGLEC15 and SIGLEC6 were in the 20 most highly expressed genes in tumor samples." (PMID 36159823, 2022). "We then systematically correlated Siglec15 with immunological characteristics in the BLCA tumor microenvironment (TME), including immunomodulators, cancer immunity cycles, tumor-infiltrating immune cells (TIICs), immune checkpoints, and T cell inflamed score." (PMID 33537076, 2021). "Eight tumor-related immunosuppressive molecules, CD274, CTLA4, HAVCR2, LAG3, PDCD1 (PD1), PDCD1LG2, SIGLEC15, and TIGIT, had higher expression in HNSCC tumor tissues compared with HNSCC normal tissues." (PMID 34917682, 2021). "In the IMvigor210 cohort, the expression of Siglec15 was higher in deserted phenotypes, TC0 (tumor cells with the lowest PD-L1 values), and IC0 (immune cells with the lowest PD-L1 values) groups." (PMID 33537076, 2021). "For one thing, Siglec‐15 is up‐regulated in tumor cells and macrophage, rather than normal tissues, implying the restricted activity within tissue microenvironment (TME)." (PMID 38725348, 2024). "SIGLEC15, PDCD1LG2 (PD-L2), TIGIT, PDCD1 (PD-1), CD274 (PD-L1), CTLA4, LAG3, and HAVCR2 (TIM3) are transcripts related to immunological checkpoints that perform a vital function in tumor immune evasion." (PMID 36042287, 2022). "SIGLEC15 was upregulated in THCA tumor tissue compared to nontumor tissue in both mRNA and protein levels; gene set enrichment analysis (GSEA) results showed that high SIGLEC15 mRNA expression was positively correlated to many immune pathways." (PMID 36159823, 2022). "SIGLEC15, PDCD1LG2(PD-L2), TIGIT, PDCD1(PD-1), CD274(PD-L1), CTLA4, LAG3, and HAVCR2(TIM3) are transcripts related to immunological checkpoints that perform vital functions in tumor immune evasion." (PMID 36253777, 2022). "SIGLEC15, PDCD1LG2 (PD-L2), TIGIT, PDCD1 (PD-1), HAVCR2 (TIM3), CTLA4, LAG3, and CD274 (PD-L1) are transcripts related to immunological checkpoints that have a function in tumor immune evasion." (PMID 36042287, 2022).
tumor (continued). "Second, we evaluated the Siglec15 and PD-L1 expression and T-cell markers such as CD4 and CD8 using TMA IHC and focused on information within SA, which may have ignored some other information regarding the tumor." (PMID 37859817, 2023). "According to our findings, Siglec15 correlated extremely well with M0 and M2 markers of TAMs (M2-type macrophages promote tumor progression) rather than M1 markers (M1-type macrophages do not promote tumor progression)." (PMID 37325664, 2023).
cancer (54 papers, 2020 to 2026). A tumor composed of atypical neoplastic, often pleomorphic cells that invade other tissues. "Previous studies have demonstrated a significant association between sialic acid binding Ig-like lectin 15 (SIGLEC15) and both the progression of malignant tumors and immune infiltration." (PMID 41158758, 2026). "TMED2 expression was positively connected with important immune checkpoint markers such as CD274, HAVCR2, PDCD1LG2, and SIGLEC15 in numerous cancer types." (PMID 40519935, 2025). "The correlation between SLC2A1 expression and eight immune checkpoints (CTLA4, PDCD1, TIGIT, LAG3, CD274, HAVCR2, PDCD1LG2, and SIGLEC15) was further investigated across multiple cancer types." (PMID 40824962, 2025). "Previous studies have indicated that SIGLEC15 mRNA plays a role in pan-cancer pathways related to immunity, metabolism, cancer, and infectious diseases, as demonstrated through GSEA." (PMID 39541298, 2024). "Here, to overcome the immune‐suppressive environment within TNBC tumors to enable more effective cancer therapy, we engineered a bispecific antibody (bsAb) targeting both Siglec15 and TGF‐β." (PMID 39553435, 2024). "Sialic acid‐binding immunoglobulin‐like lectin‐15 (Siglec‐15) has been identified as an immune suppressor and a promising candidate for immunotherapy of cancer management." (PMID 38725348, 2024). "Bioinformatics analyses were firstly performed to investigate a number of expression features of Siglec‐15 in human cancers." (PMID 38725348, 2024). "Further and thorough researches that enroll larger cancer types, explore the cellular crosstalk, and elucidate the potential mechanisms of Siglec‐15 performance are of great significance to prove and deepen our current results." (PMID 38725348, 2024). "Subsequently, we also explored the correlation between the expression levels of LRP6 and the expression levels of common immune checkpoints in 33 cancers, such as SIGLEC15, IDO1, CD274, HAVCR2, PDCD1, CTLA4, LAG3 and PDCD1LG2." (PMID 38226972, 2024). "The HPA database provided the overview of Siglec‐15 expression in 17 human cancers based on TCGA database, and the data indicated that Siglec‐15 expression was low cancer specificity." (PMID 38725348, 2024). "The investigation of SIGLEC15 as a potential target in cancer immunotherapy, highlighted by Wang’s insights, opens a promising pathway for advancing diagnostic and therapeutic approaches in COAD." (PMID 38650859, 2024). "Western blotting analysis with three LUAD samples validated that the protein level of Siglec‐15 was also up‐regulated in cancer tissues." (PMID 38725348, 2024). "We next examined the associations of TLR4 expression with 8 immune checkpoints (PD-L1, CTLA4, HAVCR2, LAG3, PDCD1, PDCD1LG2, SIGLEC15, and TIGIT), and TLR4 expression was widely associated with the 8 immune checkpoints in most cancer types." (PMID 37576399, 2023). "In a recent study, upregulated SIGLEC15 has been widely found across different cancer types and had been related to a worse patient survival rate." (PMID 38062391, 2023). "Currently, the relationship between Siglec15 expression and immune cell infiltration in different types of cancers remains uncertain." (PMID 37859817, 2023). "Based on pan-cancer analysis from The Cancer Genome Atlas database, Siglec15 was upregulated across most cancer types, including COAD23, which was consistent with our results by detecting protein expression." (PMID 37859817, 2023). "Sialic acid binding Ig-like lectin 15 (Siglec15) is considered a novel immune checkpoint and an emerging target for next-generation cancer immunotherapy." (PMID 37859817, 2023). "Sialic acid-binding Ig-like lectin 15 (Siglec-15) is an immune modulator and emerging cancer immunotherapy target." (PMID 37311743, 2023). "Siglec15, a novel immune checkpoint molecule, is an emerging target for next-generation cancer immunotherapy." (PMID 37859817, 2023).